RGL3 (ral guanine nucleotide dissociation stimulator like 3)
Description:
Guanine nucleotide exchange factor (GEF) for Ral-A. Potential effector of GTPase HRas and Ras-related protein M-Ras. Negatively regulates Elk-1-dependent gene induction downstream of HRas and MEKK1 (By similarity).
Synonyms: FLJ32585
Tractability: Antibody: its Gene Ontology location is reachable by antibodies, with medium confidence. PROTAC: ubiquitination databases record sites on it.
Gene: Protein-coding gene on chromosome 19 (11,384,341 to 11,419,352, reverse strand). Ensembl gene ENSG00000205517.
Subcellular location (Human Protein Atlas): Nucleoplasm
Pathways (Reactome):
Signal Transduction: RAF/MAP kinase cascade
Gene Ontology:
Molecular function: protein binding; guanyl-nucleotide exchange factor activity; small GTPase binding
Biological process: Ras protein signal transduction; signal transduction; small GTPase-mediated signal transduction
Cellular component: cytosol; plasma membrane
Genetic constraint (gnomAD): Loss-of-function variants: 85 observed, 86.56 expected, observed/expected ratio (o/e) 0.98, 90% interval 0.82 to 1.18. The upper end of that interval is the gene's LOEUF score, 1.18, which puts it in group 5 of 6, group 1 being the genes least tolerant of losing a copy. Missense variants: 1,029 observed, 884.02 expected, observed/expected ratio (o/e) 1.16, 90% interval 1.11 to 1.23. Synonymous variants: 407 observed, 362.18 expected, observed/expected ratio (o/e) 1.12, 90% interval 1.03 to 1.22.
Homologues: Orthologues: chimpanzee RGL3 (98% identical), macaque RGL3 (95% identical), pig RGL3 (83% identical), mouse Rgl3 (80% identical), rat Ralgdsl3 (80% identical), guinea pig RGL3 (70% identical), tropical clawed frog rgl3 (45% identical). Paralogues in human: RALGDS (41% identical), RGL1 (40% identical), RGL2 (36% identical), RAPGEF2 (19% identical), RAPGEF6 (18% identical), RAPGEF1 (17% identical), RGL4 (16% identical), RASGRF2 (15% identical), SOS2 (15% identical), SOS1 (15% identical), RASGRP4 (15% identical), RASGRP2 (15% identical), and 12 more.
Diseases named in the same sentence as RGL3 in open-access papers:
RGL3 is named in the same sentence as 16 diseases in open-access papers, as found by Europe PMC text mining. Sharing a sentence is not in itself a finding about the gene and the disease. The quoted sentences say what the papers report.
Hypertension (3 papers, 2022 to 2024). The presence of chronic increased pressure in the systemic arterial system. "A low-frequency partial deletion of RGL3 exon 6 conferred one of the strongest protective effects of gene LOF on hypertension risk (odds ratio = 0.86 (0.82–0.90))." (PMID 38548989, 2024). "According to data from earlier GWAS, rs805303 of BAG6 was associated with levels of both systolic and diastolic BP and hypertension, and rs167479 of RGL3 was associated with BP (systolic, diastolic and pulse, and mean arterial pressure) and hypertension." (PMID 36556383, 2022). "In this cohort of subjects, two SNPs of hypertension/BP genes (rs805303 of the BAG6 and rs167479 of the RGL3) were associated with PE." (PMID 36556383, 2022). "Two SNP hypertension/BP genes, rs805303 BAG6 (OR: 0.36–0.66) and rs167479 RGL3 (OR: 1.86), in subjects with preBMI ≥ 25 were associated with PE." (PMID 36556383, 2022).
colorectal cancer (1 paper, 2021). A primary or metastatic malignant neoplasm that affects the colon or rectum. "We first analyzed the transcriptional profiling of RGL subtypes RGL1, RGL2, RGL3, and RGL4 in The Cancer Genome Atlas (TCGA) colorectal cancer (CRC) database." (PMID 33917100, 2021).
diabetic retinopathy (1 paper, 2024). "Three of the 20 T2D-DMPs reached genome wide significance at FDR 5% and were located in genes with possible links to diabetic complications such as blood pressure, cardiovascular disease and diabetic retinopathy (RGL3, NGB and OTX2)." (PMID 38574408, 2024).
glaucoma (1 paper, 2023). Increased pressure in the eyeball due to obstruction of the outflow of aqueous humor. "Prioritized gene variants in our glaucoma case-control cohort supported possible causal roles in four genes for POAG (AQP5, FOXM1, SRFBP1 and CDH6) and three genes in PACG (LAMA2, ACACB and RGL3)." (PMID 36833422, 2023). "Rare, deleterious SNVs in AQP5, SRFBP1, CDH6 and FOXM1 from POAG families and in ACACB, RGL3 and LAMA2 from PACG families were found exclusively in glaucoma cases." (PMID 36833422, 2023).
melanoma (1 paper, 2021). A malignant, usually aggressive tumor composed of atypical, neoplastic melanocytes. "These are EGFR, ERRFI1, IL6, JAK2, PLXNC1, RGL3 which were found to be upregulated and CBL, CDC42, PIK3R3, STAT3, UBE2D2 and YWHAZ which were found to be downregulated; Melanoma has PLXNC1 as upregulated and TGFA as downregulated gene." (PMID 34764329, 2021).
Type 1 Diabetes (1 paper, 2024). "We found GWAS links between 7 T2D-DMP genes and T2D or related phenotypes, including SPRED2 (T2D), ITPR1 and PLD6 (Diabetic complications), SLC16A3 (BMI), TCF7 (Type 1 Diabetes), RGL3 (blood pressure) and TNIP1 (autoimmune traits)." (PMID 38574408, 2024).
tumor (2 papers, 2022 to 2023). "Other signature genes (TP63, CERS3, CSTA, CLCA2, DSC3 and DSG3) upregulated in C1 tumours are also markers of the squamous-like subtype, while further columnar-like marker genes (MUC5B and RGL3) are upregulated in C2 tumours." (PMID 36207323, 2022). "Among them, several up-regulated genes are known to be involved in the formation of tumor microenvironments (Carbonic anhydrase 2 (CA2)), cancer chemoresistance (Cannabinoid receptor 1 (CNR1), GFRA1) and cancer recurrence after therapy (RGL3)." (PMID 36769365, 2023).
RGL3 also shares sentences with these, for which no sentence is quoted: infection (2 papers); preeclampsia (2); Bladder cancer (1); cancer (1); cardiovascular disease (1); endometrial cancer (1); gestational diabetes (1); non-small cell lung carcinoma (1); pregnancy hypertension (1).